PDPN (podoplanin)
Diseases named in the same sentence as PDPN in open-access papers (continued):
Sharing a sentence is not in itself a finding about the gene and the disease.
soft tissue tumors (2 papers, 2017 to 2021). "In order to compared the performance of FDCSP and SRGN with known FDC-S markers in the differential with soft tissue tumors, we tested CD21, CD23, CD35, CXCL13, Clusterin, Claudin 4 and Podoplanin in our groups of tumors and controls." (PMID 28145886, 2017).
squamous intraepithelial lesions (2 papers, 2016 to 2017). "We first detected the expression of PDPN positive basal cell layer in low-grade squamous intraepithelial lesions." (PMID 28086225, 2017). "To test this hypothesis, we detected the expression of PDPN protein in different stages of squamous intraepithelial lesions." (PMID 28086225, 2017).
tendinopathy (2 papers, 2017 to 2022). "Tissues and cells derived from patients with tendinopathy show increased expression of markers of stromal fibroblast activation including Podoplanin (PDPN), VCAM-1 (CD106) and Endosialin (CD248) compared to healthy tendon tissues and cells." (PMID 28887458, 2017). "Furthermore, immunostaining for markers of enzymes implicated in inflammation (PDPN/15PGDH/COX2) and receptors and enzymes implicated in resolution (PDPN/ERV1/ALOX12) revealed expression of these proteins in early tendinopathy." (PMID 38655164, 2022). "Incubation of tendon-derived stromal cells from both healthy volunteers and patients with tendinopathy in SPM including 15-epi-LXA4 or MaR1 induced further release of proresolving mediators and counter regulated the expression of pro-inflammatory molecules including PGE2, IL-6, STAT-1 and PDPN." (PMID 28887458, 2017).
testicular cancer (2 papers, 2017 to 2025). A primary or metastatic malignant neoplasm that affects the testis. "However, with regard to testicular cancer, there are no reports of POSTN expression in human and canine testicles, and there are only two studies on PDPN in humans." (PMID 41361308, 2025).
thyroid tumor (2 papers, 2014 to 2019). A benign or malignant neoplasm affecting the thyroid gland. "We found that PDPN-induced cell phenotype depended on the genetic background of thyroid tumor cells." (PMID 30654768, 2019). "In light of its pro-invasive properties reported in other types of human tumors and the high levels detected in PTC samples, we next investigated whether PDPN is involved in the migration and invasion of thyroid tumor cells." (PMID 24797369, 2014). "The expression of podoplanin was first evaluated in archived thyroid tumor tissue samples." (PMID 24797369, 2014). "Hence, the aim of this study was to characterize the expression and function of podoplanin in thyroid tumors biology." (PMID 24797369, 2014).
type 1 diabetes (2 papers, 2021). "Podoplanin staining was limited to lymphatic vessels (not shown) in NOD mouse and human pancreases but was present in inflamed islets in pancreases of both humans with type 1 diabetes and NOD mice." (PMID 33912981, 2021).
ulcer (2 papers, 2021). "In situ localization of inflammatory fibroblasts by PDPN and FAP revealed their proximity to neutrophils in ulcers." (PMID 34675383, 2021).
viral infection (2 papers, 2016 to 2019). "In contrast, we find that cell-specific loss of TLR7 in podoplanin+ cells fails to influence early viral infection in dLN." (PMID 30930901, 2019).
adamantinoma (1 paper, 2025). A low grade malignant neoplasm arising from the long bones. "Recent studies suggest that OFD, OFD-like adamantinoma, and classic adamantinoma represent a spectrum with shared cytogenetic findings (trisomies of chromosomes 7, 8, and 12) and podoplanin expression." (PMID 40860805, 2025).
adhesive capsulitis (1 paper, 2019). "Further sub analysis of tissue distribution revealed that PDPN was most abundantly expressed in adhesive capsulitis with approximately 60% of cells positive versus 40% in control tissues followed by CD248 (60% versus 25% control, p<0.01) and VCAM (20% versus 5% control, p<0.01)." (PMID 31013287, 2019).
anaplastic oligodendroglioma (1 paper, 2016). A WHO grade III oligodendroglioma with focal or diffuse malignant morphologic features (prominent nuclear pleomorphism, mitoses, and increased cellularity). "Our gene signature also contained proneural genes, BMP2, DCX, IGFBP2, PDPN, and PLAT, which are associated with anaplastic oligodendroglioma harboring 1p/19q co-deletion." (PMID 27323413, 2016).
Anxiety (1 paper, 2019). Intense feelings of nervousness, tension, or panic often arise in response to interpersonal stresses. "In addition, mice with podoplanin gene disruption showed increased anxiety-like behaviors in experimentally validated behavioral tests as compared to wild type littermate controls." (PMID 32009902, 2019).
bacterial sepsis (1 paper, 2025). "We next assessed ADAP-dependent LPS-induced PDPN expression in the PMs in the context of bacterial sepsis." (PMID 39903516, 2025). "The next question is whether ADAP-dependent LPS-induced PDPN expression can also be applied to generate an inducible subset of PDPN+ macrophages in vivo in the context of bacterial sepsis." (PMID 39903516, 2025).
bladder tumor (1 paper, 2017). "Therefore, the significant expression of SLP-76, together with that of LYVE-1 and PDPN, observed in our cohort of patients led us to believe that its role in bladder tumor spreading might be preeminent and deserves further investigation." (PMID 28423532, 2017).
bone metastasis (1 paper, 2015). Transfer of a neoplasm from its primary site to bones. "Stromal podoplanin, S100A4, and PDGFRα expression was elevated in bone metastasis, while tumoral podoplanin and stromal PDGFRβ expression was elevated in lung metastasis." (PMID 26163388, 2015).
breast adenocarcinoma (1 paper, 2015). "The localisation of podoplanin at invadopodium rings was also confirmed in MDA-MB-231 breast adenocarcinoma cells upon podoplanin ectopic expression." (PMID 25486435, 2015).
chorioamnionitis (1 paper, 2019). A morphologic finding indicating inflammation of the fetal sac membranes. "Additionally, podoplanin immunoreactivity was not correlated with the localization or severity of placental inflammation (chorioamnionitis and/or funisitis and/or chorionic vasculitis)." (PMID 31578434, 2019).
Chronic colitis (1 paper, 2020). A chronic inflammatory disease of the large intestine (colon, cecum and rectum). "Markedly, FAP and PDPN were highly increased in the inflamed tissue of DSS-induced chronic colitis, which might be a hint for the pathogenesis of intestinal fibrosis and the underlying mechanism of berberine." (PMID 32332711, 2020).
chronic heart failure (1 paper, 2020). "In addition, human heart samples were obtained from healthy donors or patients with chronic heart failure, and the gene expression of lymphatic endothelial markers VEGFC, LYVE1, PDPN, and FLT4 was assessed." (PMID 33200983, 2020).
chronic lung disease (1 paper, 2014). According to the definitions of the American and British Thoracic Societies, including pulmonary functional tests, X-rays, and CT scans for items such as fibrosis, bronchiectasis, bullae, emphysema, nodular or lymphomatous abnormalities. "Moreover, we examined pulmonary lymphatic development in the setting of chronic lung disease (CLD) by quantifying podoplanin staining at the acinar level in subjects with and without CLD." (PMID 24527433, 2014).
cognitive decline (1 paper, 2025). "In conclusion, our study identifies PDPN as a novel player in T2DM-induced neuroinflammation and cognitive decline." (PMID 39911382, 2025).
dermatitis (1 paper, 2020). An inflammatory process affecting the skin. "We investigated the number of CD34-positive blood vessels and podoplanin (recognized by the D2–40 antibody)-positive lymphatic vessels in nipple tissue in Paget disease, dermatitis, and healthy tissues." (PMID 32527320, 2020). "We calculated the average CD34-positive BVD and podoplanin (D2–40)-positive lymphatic vessel density (LVD) and the proportion of proliferating of endothelial cells in 14 Paget disease, 3 dermatitis biopsy, and 14 age-matched control cases." (PMID 32527320, 2020).
developmental delays (1 paper, 2026). "Altered glycosylation of integrins (ITA7, LG3BP) and the upregulation of PDPN may further destabilize these critical cell-ECM interactions, potentially explaining the developmental delays and seizure phenotypes observed in ALG13-CDG." (PMID 41597222, 2026).
diabetic encephalopathy (1 paper, 2025). A brain disease that is characterized by functional impairment of cognition, cerebral signal conduction, neurotransmission and synaptic plasticity, and underlying structural pathology associated with diabetes. "Future studies should aim to elucidate the precise molecular mechanisms underlying the PDPN-mediated inflammatory response in T2DM astrocytes and explore the therapeutic potential of targeting PDPN in the treatment of diabetic encephalopathy." (PMID 39911382, 2025). "Our results revealed a significant increase in PDPN expression in astrocytes isolated from T2DM mouse models, suggesting a potential link between this glycoprotein and the pathological processes underlying diabetic encephalopathy." (PMID 39911382, 2025).
diabetic foot ulcers (1 paper, 2022). "Therefore, podoplanin could have therapeutic potential in patients with impaired wound healing (e.g., diabetic foot ulcers) when upregulated in the keratinocytes at the wound edge." (PMID 35163233, 2022).
diffuse astrocytoma (1 paper, 2022). A low-grade (WHO grade II) astrocytic neoplasm. "This may be particularly true with respect to the low-grade diffuse astrocytoma analysis, as PDPN mRNA was detected by qRT-PCR in the low-grade tumors in that study." (PMID 36059614, 2022).
Disseminated intravascular coagulation (1 paper, 2020). Disseminated intravascular coagulation is characterized by the widespread activation of coagulation, which results in the intravascular formation of fibrin and ultimately thrombotic occlusion of small and midsize vessels. "Interestingly, overexpression of PDPN in mice leads to disseminated intravascular coagulation, a condition that is strikingly similar to that seen in many dogs with HSA." (PMID 32571313, 2020).
ductal breast carcinoma (1 paper, 2007). "Such a novel mechanism of invasive tumor cell dissemination, which has also been proposed for podoplanin, may be clinically important in the most prevalent ductal breast carcinoma subtype as these tumors rarely undergo dissemination by a recognizable epithelial to mesenchymal transformation." (PMID 17311105, 2007).
ductal carcinoma in situ (1 paper, 2020). "In addition, the results of clinical studies showing the presence of a higher number of podoplanin-rich BCAFs in IDC than in ductal carcinoma in situ (DCIS), further corroborate the pivotal role of podoplanin-positive BCAFs in BC progression and dissemination." (PMID 32604738, 2020).
dysgerminomas of the ovary (1 paper, 2007). "Podoplanin was found expressed in dysgerminomas of the ovary and in granulosa cell tumours." (PMID 17179989, 2007).
eccrine carcinoma (1 paper, 2025). An adenocarcinoma with eccrine differentiation arising from the sweat glands. "Emerging markers such as podoplanin (D2-40) and androgen receptor (AR) have been explored in distinguishing eccrine carcinoma subtypes, though their utility in SEDC remains unclear." (PMID 40282903, 2025).
ependymoma (1 paper, 2023). A WHO grade II, slow growing tumor of children and young adults, usually located intraventricularly. "Immunohistochemistry should be performed for EMA or podoplanin, GFAP, BCOR, and p65-RELA or L1CAM for ZFTA-RELA ependymomas." (PMID 36604386, 2023).
epilepsy (1 paper, 2021). A brain disorder characterized by episodes of abnormally increased neuronal discharge resulting in transient episodes of sensory or motor neurological dysfunction, or psychic dysfunction. "This indicates that PDPN and ABCC3 are risk genes, and INA is a protective gene for LGG patients with epilepsy." (PMID 34336837, 2021). "This suggests that the hypomethylation of ABCC3 and PDPN is present in LGG patients with epilepsy who have high immune score and poor prognosis." (PMID 34336837, 2021). "An immune-related gene signature was established based on ABCC3, PDPN, and INA, which can be used to predict the prognosis, immune infiltration status, immunotherapy and chemotherapy response of LGG patients with epilepsy." (PMID 34336837, 2021). "Further, three prognostic DEGs (ABCC3, INA, and PDPN) were identified between high and low immune score groups in LGG patients with epilepsy." (PMID 34336837, 2021). "In this study, the high expression of ABCC3 and PDPN genes was found in the high immune score group and was related to the poor prognosis of LGG patients with epilepsy." (PMID 34336837, 2021).
Epiretinal membrane (1 paper, 2021). An epiretinal membrane is a thin sheet of fibrous tissue on the surface of the retina along the inner limiting membrane. "BS, BPM, and VC specimens were selectively collected in macular hole and epiretinal membrane patients during vitrectomy and were then immunostained with antibodies for podoplanin, LYVE-1, and fibrillin-1 and -2." (PMID 33669860, 2021).
erythroplakia (1 paper, 2025). "Podoplanin overexpression was significantly associated with an increased risk of malignant transformation of erythroplakia (RR = 6.31, 95% CI = 1.02–38.98, p = 0.05)." (PMID 41228241, 2025).
esophagus carcinoma (1 paper, 2019). "The podoplanin expression level in these cells was more than 5-fold the expression level in esophagus carcinoma TE11 cells, which are reported to express relatively high levels of podoplanin compared with other carcinoma cell lines." (PMID 31553741, 2019).
gastric tubular adenocarcinoma (1 paper, 2024). A variant of gastric adenocarcinoma characterized by prominent dilated or slit-like tubules. "Kondo and colleagues observed that podoplanin-expressing CAFs positively affected the invasion of both gastric signet ring cells and gastric tubular adenocarcinoma cells." (PMID 38562556, 2024). "However, silencing podoplanin did not affect the invasion of aggressive gastric signet ring cells despite decreasing the invasion of gastric tubular adenocarcinoma cells." (PMID 38562556, 2024).
gastric tumor (1 paper, 2025). "Through an unbiased integrated analysis of gastric tumor grade and stage, we identified a subset of proangiogenic CAFs characterized by high podoplanin (PDPN) expression, which are significantly enriched in metastatic lesions and secrete chemokine (CC‐motif) ligand 2 (CCL2)." (PMID 39764562, 2025).
hepatocellular carcinoma (1 paper, 2024). A malignant tumor that arises from hepatocytes. "This study aimed to analyze the expression of Ang2, podoplanin, and CLEC-2 proteins to better understand the outcomes of patients with advanced hepatocellular carcinoma (HCC) undergoing TKI treatment." (PMID 39061998, 2024).
HER2 positive breast carcinoma (1 paper, 2024). A biologic subset of breast carcinoma defined by high expression of HER2, GRB7, and TRAP100, and by lack of expression of estrogen receptor (ER). "It has been shown that PDPN-positive CAF can promote resistance to trastuzumab in Her2-positive breast cancer by secreting the immunosuppressive factors indoleamine 2,3-dioxygenase 1 (IDO1) as well as tryptophan 2,3-dioxygenase 2 (TDO2)." (PMID 38728370, 2024).
Hodgkins lymphoma (1 paper, 2024). A heterogeneous group of malignant lymphoid neoplasms of B-cell origin characterized histologically by the presence of Hodgkin and Reed-Sternberg (HRS) cells in the vast majority of cases. "We demonstrated that Hodgkin lymphoma cells, which endogenously express CA9, but not PDPN, induce CLEC2 signaling." (PMID 39768175, 2024).
immune deficiency (1 paper, 2023). "Furthermore, podoplanin expression in CAFs promotes LAD engraftment into SCID mice (which have a genetic immune deficiency owing to an autosomal recessive mutation), thereby affecting B and T cells." (PMID 36376711, 2023).
influenza (1 paper, 2023). An acute viral infection of the respiratory tract, occurring in isolated cases, in epidemics, or in pandemics; it is caused by serologically different strains of viruses (influenzaviruses) designated A, B, and C, has a 3-day incubation period, and usually lasts for 3 to 10 days. "Cdh5CreERT2; ROSA26LSL-tdTomato; Atf3lox/lox (Atf3EC-KO) and control Cdh5CreERT2; ROSA26LSL-tdTomato (Atf3EC-WT) mice were subjected to influenza injury and assessed at 14 and 21 dpi for PDPN expression to define alveolar architecture." (PMID 37233732, 2023).
Insulin resistance (1 paper, 2019). Increased resistance towards insulin, that is, diminished effectiveness of insulin in reducing blood glucose levels. "Solute carrier family 9, member 3 regulator 1 (SLC9A3R1), PODXL, and PDPN are novel biomarkers for the development of insulin resistance." (PMID 30678306, 2019).
kidney cancer (1 paper, 2024). Primary or metastatic malignant neoplasm involving the kidney. "We further see that lymphoid aggregates co-localize with PDPN+ lymphatic vessels at the tumor border, similar to observations in kidney cancer." (PMID 38361951, 2024).
leiomyosarcoma (1 paper, 2014). An uncommon, aggressive malignant smooth muscle neoplasm, usually occurring in post-menopausal women. "Again, in leiomyosarcomas, podoplanin-positive vessels are especially found in tumours with lymph node metastases." (PMID 24398114, 2014).
leprosy (1 paper, 2013). Leprosy is a chronic infectious disease affecting primarily the skin and peripheral nervous system. "The aim of this study was to evaluate angiogenesis and lymphangiogenesis across the spectrum of leprosy, in its reactional episodes and in its residual lesions by immunohistochemistry (IHC), using the markers CD31, CD105/endoglin and D2-40/podoplanin." (PMID 24040306, 2013).
leukocytosis (1 paper, 2024). "Indeed, this finding is consistent with previous studies showing that the landscape of cancer coagulome expression varies significantly among different cancer types, with varying levels of tissue factor (TF), podoplanin (PDPN), inflammatory mediators, leukocytosis, and platelet counts." (PMID 38955935, 2024).
lipomatosis (1 paper, 2006). A neoplastic process characterized by diffuse overgrowth of mature adipose tissue. "Although the littoral cells of the marginal and trabecular sinuses were very focally and faintly immunoreactive for podoplanin, no intranodal podoplanin immunoreactive vascular structures were demonstrated except in trabecular septa or areas of lipomatosis and fibrosis." (PMID 17088912, 2006).
lymphatic disease (1 paper, 2011). "In the future, the combination of molecular markers with proven predictive value for lymphatic disease like ECAD, podoplanin, p16, bmi-1, LOX and histopathological features could allow an individual risk stratification with possible impact on treatment strategy." (PMID 21639893, 2011).
Lymphatic Metastasis (1 paper, 2025). Transfer of a neoplasm from its primary site to lymph nodes or to distant parts of the body by way of the lymphatic system. "Definitive identification of the metastatic route requires additional immunohistochemical analysis: lymphatic metastasis is typically associated with D2-40 (podoplanin) positivity, whereas hematogenous metastasis shows CD34 positivity." (PMID 41584594, 2025).
malignant tumors of salivary glands (1 paper, 2019). "This study aimed to investigate the immunohistochemical expression of CD31 and podoplanin in order to examine angiogenesis and lymphangiogenesis, respectively in common malignant tumors of salivary glands." (PMID 31870093, 2019).
mast cell tumors (1 paper, 2020). "In addition, there are no reports on the expression of PDPN in human mast cell tumors and peripheral nerve sheath tumors, which are rare in humans." (PMID 32380790, 2020).
memory impairment (1 paper, 2025). "Notably, the knockdown of PDPN expression significantly ameliorated the memory impairment observed in 28-week-old T2DM mice." (PMID 39911382, 2025).